IFNG (interferon gamma)
Diseases named in the same sentence as IFNG in open-access papers (continued):
Sharing a sentence is not in itself a finding about the gene and the disease.
tumor (continued). "PD-1, another marker of T cell exhaustion, is expressed at a characteristically high level in tumor infiltrating T cells, which is in consistent with a reduction in interleukin (IL)-2 and IFNγ production and cell cycle arrest in T cells." (PMID 31824865, 2019). "Studies from patients resistant to anti-PD1 therapy have also provided strong support for ICB-induced IFNγ action directly on tumor cells." (PMID 30948928, 2019). "The tumor cell growth conditions had a strong influence on the level of IFNγ secretion with a substantially higher MesobsFab-mediated release of IFNγ during 3D ADCC (10 to 40-fold) compared to 2D ADCC at different E:T ratio." (PMID 31354732, 2019). "Vertebrates generate specific immune responses against malignant tumor cells such as the production of IFNγ and tumor-specific cytotoxic CD8 T cells." (PMID 30972427, 2019). "IFNG produced by immune cells in the tumor environment plays an important role in recruiting CD8 T cells and in NK cell infiltration." (PMID 31998649, 2019). "To determine if altering the sensitivity of LLC cells to IFNγ affects tumor growth in vivo and responsiveness to anti–PD-1, we implanted equal numbers of LLC-NT or LLC-sh21 cells into the lungs of syngeneic WT mice." (PMID 31133614, 2019). "Various polarization signals like IFNγ and bacterial LPS activate M1 macrophages and once activated, they detect and clear tumor cells, pathogens and also present antigens to T cells." (PMID 30925924, 2019). "This complex molecular structure reduces IFNγ diffusion through the tumor matrix and the chemokine gradient that is necessary to favor T lymphocytes migration into the tumor." (PMID 30935099, 2019). "Its increased expression on tumor cells leads to tumor progression (proliferation) and metastasis, and its expression is dependent on TNFα, IL-1β, IFNγ via toll-like receptors (TLRs)." (PMID 31374832, 2019). "The main factors in T cells anti-tumor cytotoxicity include IFNγ, granzyme B, and perforin secretion." (PMID 31514488, 2019). "Regarding the tumor cell intrinsic mechanism of antitumor, many studies demonstrated that IFNγ signaling exerts antitumor role mainly involved in anti-proliferative and pro-apoptotic processes." (PMID 31113461, 2019). "Adenosine inhibits NK cell anti-tumor activities by blocking granzyme exocytosis, impairing perforin and Fas ligand-mediated cytotoxic activity and limiting IFNγ/TNFα release." (PMID 31057536, 2019). "For instance, the anti-tumor potency of some adoptively transferred T cells was shown to rely on the IFNγ-dependent activation of TAM." (PMID 31354719, 2019). "Aside from the role of IFNγ in immunoediting, thereby preventing primary tumor formation, defects in both IFN and TNF signaling have been associated with increased cancer risk." (PMID 30833945, 2019). "CD8+ T cells enhance antigen presentation by increasing the expression of MHC class I antigens by tumour cells through the production of IFNγ and kill tumour cells with cytotoxic granzymes and perforin." (PMID 30944831, 2019). "Following the release of interferon gamma (IFN-γ), tumor cells express PD-L1, which binds with PD-1-expressing T cells, and thus IFN-γ renders T cells inactive and allows tumors to evade the immune response." (PMID 31371782, 2019). "Surprisingly, we also detected a few IFNγ‐producing CD8 T cells upon stimulation with the N‐peptide in tumor tissues of DCVacc treated mice." (PMID 30972741, 2019). "A panel of MET-amplified tumour cell lines from different tissue origins has been analysed for IFNγ-inducible PD-L1/PD-L2 expression." (PMID 30723303, 2019). "CD46 activation on γδ T-cells has also been shown to directly suppress their IFNγ and TNFα production, which can further lead to a pro-tumor environment." (PMID 31164885, 2019). "We further demonstrated in the current study that the DCG administration results in increased levels of IFNγ/IL-10 in the spleen and increased IFNγ/IL-9 secreting T cells infiltrating to the tumour site." (PMID 31183361, 2019).
tumor (continued). "M1 macrophages, in response to IFNγ or TNFα, convert arginine into nitric oxide (NO) through inducible nitric oxide synthase (iNOS) to promote anti-tumor activity." (PMID 31462642, 2019). "Our observations include induction of immunogenic cell death in a small fraction of tumor cells and objective immunotherapeutic activity dependent on Interferon-γ (IFNγ) and type-I interferon." (PMID 31046839, 2019). "Peripheral and tumor-associated NK cells in STAT3-targeted tumor-bearing mice, exhibit higher expression of the NK activation markers NKG2D, CD69, Fas ligand (FasL), granzyme B, perforin, and IFNγ, resulting in reduced tumor growth and enhanced survival." (PMID 31057536, 2019). "Here, we demonstrated that F1 leads to NK cell activation via IL-15 upregulation, associated with increased granzyme B and perforin production to eliminate tumor cells, as well as higher levels of the antitumor IFNγ cytokine." (PMID 30717773, 2019). "Whereas, CD80−PD-L1+ human tumor cells anergized activated PD-1+ human PBMC and inhibited their production of IFNγ, CD80+PD-L1+ human tumor cells prevented anergy and maintained IFNγ production." (PMID 31001479, 2019). "IL12p70 is a prominent inducer of anti-tumor immunity mostly through the stimulation of natural killer (NK) cells and cytotoxic T lymphocytes (CTLs) and their subsequent secretion of IFNγ." (PMID 30679720, 2019). "NKp46-mediated IFNγ secretion increases the expression of fibronectin 1 (FN1) by tumor cells leading to ECM structural changes in the primary tumors and decreased metastasis." (PMID 32117199, 2019). "On the other hand, Th1 responses have been described to promote M1 differentiation in early tumor stages through secretion of IFNγ." (PMID 30853959, 2019). "In cancers triggered by viruses (e.g., cervical cancer) or by bacteria (e.g., stomach cancer), we would expect an activation of ILC1s, the production of IFNγ and TNFα, leading to anti-tumor immune responses." (PMID 31024531, 2019). "A recent study conducted in a murine sarcoma model showed that TANs acting in concert with macrophages, were essential for unconventional αβ T cell type 1 polarization to display anti-tumor potential in vivo by secreting IFNγ." (PMID 31616408, 2019). "Activation of the JAK1-dependent interferon gamma (IFNγ) signaling pathway is known to have direct effects on tumor cells, impacting numerous cell programmes including growth, apoptosis, proliferation, differentiation and migration." (PMID 31552026, 2019). "Many studies have reported various blockage in immune checkpoints that can lead to up-regulation of Interferon gamma (IFNγ) and further lead to tumor cell progression." (PMID 31540128, 2019). "On the other hand, chemokines orchestrate tumor homing of cells that are the major producers of IFNγ, such as Th1-polarized CD4+ T, CD8+ T cells, and NK cells." (PMID 30873179, 2019). "The synergistic effect of the combined treatment involved improved T cell effector function as well as reduced CD73 expression on tumor-infiltrating lymphocytes and was dependent on interferon gamma (IFN-γ) and perforin." (PMID 31024543, 2019). "TANs can alter the tumor microenvironment (TME) by secreting inflammatory cytokines such as IFNγ and TNFα that potentiate the local immune infiltrates and systemic response." (PMID 31131086, 2019). "Though conventionally known for its anti-tumor properties, interferon-gamma (IFN-γ) has pro-tumorigenic roles as well." (PMID 31769418, 2019). "In mouse LUADs, Treg depletion resulted in tumor cell death and increased levels of granzyme A, granzyme B, perforin, and IFNγ in infiltrating CD8+ T cells, suggesting Tregs inhibit the antitumor function of CD8+ T cells." (PMID 32039025, 2019). "Inhibition of p38 restored the IL-12:IL-10 balance in Dex or tumor lysate-conditioned healthy cDC2 and enhanced T-cell proliferation and interferon-gamma (IFNγ) production." (PMID 31143512, 2019).
tumor (continued). "In mice, depending on the tumor model, different TAN-derived soluble factors were reported to suppress proliferation and IFNγ production of intra-tumor CD8+ T-cells, such as ROS or nitric oxide (NO) produced by inducible nitric oxide synthase (iNOS)." (PMID 31616408, 2019). "For example, MSCs were reported to be engineered to highly express IL-12, IL-21 or IFNγ to enhance tumor targeting." (PMID 31320999, 2019). "Recent research found that BACH2 promotes tumor immunosuppression via IFNγ and Treg-mediated intratumoral CD8+ T cell inhibition." (PMID 31824865, 2019). "We thus explored the IFNγ-inducible PD-L1/PD-L2 expression in MET-amplified tumours, along with its potential modulation by treatment with MET-inhibitors." (PMID 30723303, 2019). "CD8+ T-cell tumor infiltration and tumoral gene expression of IFNG, CD8A, CXCL9, and granzyme K (GZMK) were also increased following MEDI0680 administration." (PMID 31439037, 2019). "RNA-LPX encoding for a viral or mutant neoantigen can induce strong memory T-cell responses and lead to IFNγ-mediated tumour regression." (PMID 31091774, 2019). "As a result of adaptive immune resistance, PD-L1 overexpression on tumor cells is induced by IFNγ that is produced by activated T cells." (PMID 31824865, 2019). "Apart from its general immunomodulatory activity, IFNγ plays also an important role in tumor surveillance." (PMID 31457007, 2019). "Peripheral and tumor-associated NK cells from STAT3-targeted tumor-bearing mice expressed elevated levels of NK activation markers NKG2D, CD69, Fas ligand (FasL) granzyme B, perforin, and IFNγ, resulting in reduced tumor growth and enhanced survival." (PMID 31057536, 2019). "ANF in combination with PD-L1 blockade exerted potentiated effects in induction of infiltration of CD3, CD8, CD4, and B220 positive cells into tumor tissues, and upregulation of IFNγ and TNFα expression by the lungs." (PMID 30850589, 2019). "Inflammatory Th17 produce IFNγ and IL-17 and exert anti-tumor effects while regulatory Th17 secrete IL-10 and IL-17 and transform ATP into the immunosuppressive molecule adenosine thus sustaining tumor development." (PMID 31024531, 2019). "CD4+IFNγ+ T cells were elevated in tumor in both CB-MSC monotherapy and combination treatment groups." (PMID 31320999, 2019). "After 48 hours of CD20xCD3 bsAb treatment, T cells cultured with a mixture of JeKo-1 and RL tumor cells strongly up-regulated IFNγ and Granzyme B, indicating that the T cells were effectively activated." (PMID 31882897, 2019). "Both CD4+ and CD8+ T cells cultured with Raji or JeKo-1 tumor cells exhibited increased expression of the effector molecules Granzyme B and IFNγ." (PMID 31882897, 2019). "CAR-147 macrophages significantly increased the levels of IL-12 and IFNγ, which can exert potent anti-tumour responses, in the tumour tissue." (PMID 31570753, 2019). "Then, we assessed the secretion of cytokines important for anti-tumor T cells responses, namely TNFα, IFNγ and IL-2." (PMID 31500665, 2019). "Among the predicted upstream regulators, we found IL-21, IFNA, and IFNG, factors reported to have antitumor effects in a variety of murine experimental tumor models." (PMID 31710308, 2019). "In contrast, lymphocytes enhance the anti-tumor efforts by secreting cytokines, such as interferon gamma (INF-γ) and tumor necrosis factor (TNF-α), thereby promoting cytotoxic cell death." (PMID 31620369, 2019). "We concluded that OGD culture conditions induced the activation of the PI3K/AKT pathway in tumor cells and thereby blocks IFNγ responsiveness." (PMID 31196219, 2019). "Our results also revealed that ex vivo stimulation of Nrp-1+PD-1hi TIL with autologous tumour cells induced higher percentages of IFNγ-producing T cells than in Nrp-1−PD-1− and the Nrp-1−PD-1+ TIL subsets." (PMID 31350404, 2019). "It is expected that cytokine production by an active immune infiltrate, represented by the Teff signature, will lead to downstream IFNγ signaling within tumor cells." (PMID 31125352, 2019).
tumor (continued). "TNFα and IFNγ, for example, were shown to have both promoting and inhibitory effects on tumor growth." (PMID 30833945, 2019). "Consistently, Tlr4−/− mice also showed reduced tumor reactive T cells and IFNγ production compared with WT mice when vaccinated with the identical dying cells." (PMID 31324798, 2019). "Quantification of BrdU-labeled cells, normalized for tumor area, revealed a significant reduction of cell proliferation in the tumoral region of LPS/IFNγ-MV treated mice." (PMID 30853898, 2019). "The tumours of mice treated with this triple combination therapy had increased frequencies of mature DCs and IFNγ+ and TNFα+ CTLs." (PMID 31091774, 2019). "FIP200 deletion induced an anti-tumor immune response mediated by CD8+ and CD4+ T cell infiltration to the tumor site, mediated by IFNγ and chemokine secretion (CXCL9, CXCL10, CXCL11) by autophagy-deficient tumor cells." (PMID 31554173, 2019). "Once generated in the draining lymph nodes, LLC-specific effector CD4 (Th1) and CD8 (CTLs) would migrate into tumor tissue to produce IFNγ and kill tumor cells." (PMID 30972427, 2019). "Lycopene treatment increased the CD4+/CD8+ ratio in the spleen and promoted IFNγ-expressing CD8+ T cells in tumor tissues." (PMID 30948928, 2019). "In vivo, tumor cells can mediate adaptive resistance by upregulating PD-L1 in response to interferon-gamma (IFNγ) released by the cytotoxic T lymphocytes within the tumor bed." (PMID 30951669, 2019). "Adapter doses below 0.01 nM exerted little effect on tumor cell lysis and only minimal effect on IFNγ production." (PMID 31213606, 2019). "To further explore the effect of PD-L1 expression in cancer resistance to IFNγ producing CTLs that express PD-1,31 we investigated the regulation of PD-L1 transcription in all tumor cell lines by qRT-PCR in vitro." (PMID 31481761, 2019). "Another group showed that pro-inflammatory cytokines TNFα, IL-6, CSF-1, and IFNγ correlated with disseminated tumor cells in BC18." (PMID 30814616, 2019). "Combined use of ANF and anti-PD-L1 antibody significantly increased infiltration of CD8+, CD4+, and CD3+ T lymphocytes into tumor tissues, and upregulated the expression of IFNγ and TNFα." (PMID 30850589, 2019). "Targeting sMIC with B10G5 increased NK cell number in the peripheral and tumor infiltrates and augmented NK cell intrinsic function as measured by the ability to produce IFNγ in response to PMA and Ionomycin (PMA/I) stimulation." (PMID 31446896, 2019). "MSI-positive tumors presenting neoantigens promote the release of IFNγ from tumor-infiltrating lymphocytes, which enhances PD-L1 expression in tumors and immune cells." (PMID 30941308, 2019). "In conjunction with IL-6, IFNγ plays a major role in modulation of the cancer immune network to inhibit or promote tumor progression." (PMID 30666202, 2018). "It induces CD8+ T cells antitumor immunity, decreases the percentage of Tregs in the tumor, increases the levels of interferon-gamma (IFNγ) and reduces those of IL-6, IL-10, and VEGF, as shown in renal tumor model." (PMID 30134816, 2018). "The IFNγ signaling pathway acts as a double-edged sword, with critical roles in mediating the degree and extent of anti-tumor immune response, and by extension, the efficacy of immune checkpoint therapy." (PMID 29968076, 2018). "Here, the adoptively transferred tumor-reactive T cells were generated from GREAT mice which express YFP on the IFNγ promoter." (PMID 30333482, 2018). "This enhanced tumor killing activity of T cells is also supported by increased levels of granzyme B and IFNγ in the media." (PMID 30324091, 2018). "The proportions of CD8+IFNγ+ T cells in the tumor immune infiltrate were also increased in Poly I:C-treated WT and PLT2 mice." (PMID 30383838, 2018).
tumor (continued). "Activation via 2 strong stimuli, such as α-GalCer and IL-12, increases iNKT cell IFNγ production, promotes tumor rejection, and protects from development of metastasis in multiple mouse models and enhances cancer patient iNKT Th1 responses in vitro." (PMID 29559971, 2018). "IL-12-LNP elicited marked infiltration of activated CD44+ CD3+ CD4+ T helper cells into the tumor, and increased the production of Interferon γ (IFNγ)." (PMID 30458889, 2018). "Immune cell populations in the spleens and tumors were evaluated by flow cytometry and the frequency of tumor antigen-reactive IFNγ-producing CD8+ T cells was evaluated by an ELISpot assay in the MC38 model." (PMID 30400835, 2018). "In the metastatic phase, B220+CD11c+NK1.1+HepELs with high IFNγ activity attack migrating metastatic tumour cells in the lung." (PMID 29930175, 2018). "A significantly lower proportion of NK cells within tumors and liver were able to produce IFNγ than in the blood; in four out of six cases, production was even lower within the tumor than the uninvolved liver." (PMID 29867983, 2018). "In particular, CTL specific for tumor-associated antigens (TAA), together with Th1 and NK cells expressing IFNγ, guide immunity against the tumor promoting tumor cell apoptosis, and releasing effector cytokines and cytotoxic molecules." (PMID 30319638, 2018). "Here, we have used DE50 values to describe TCR repertoire analysis and find good correlations with the strength of the IFNγ venus signals we measured as an indicator of effector function of CD8+ T-cells in the tumor." (PMID 29348598, 2018). "Established human tumor cell lines rarely express surface PD‐L1, but IFNγ treatment can induce most of the cell lines to express high levels of surface PD‐L1." (PMID 30039553, 2018). "The perivascular T-cells in turn induced the expression of PD-L1 in tumor endothelial cells via IFNγ, which was utilized when additionally PD-1 blockade improved tumor control by the bispecific antibody in the different cancer models." (PMID 30250827, 2018). "Recently, there are several papers regarding factors that can regulate IFNγ expression in tumor‐infiltrating NK cells and T cells." (PMID 30039553, 2018). "This immune escape mechanism was corroborated by findings in gastric and ovarian cancer cell lines that stromal CD8+ infiltration levels are correlated with both IFNγ levels and tumor PD-L1 expression." (PMID 30497521, 2018). "Results from this analysis are consistent with prior knowledge of EGFR-mutant NSCLC, demonstrating a PD-L1 low, GzmB low, IFNG low and TGFbeta high immune phenotype, suggesting a suppressive tumor microenvironment." (PMID 30400822, 2018). "Compared to WT mice, the Tbkbp1-KO mice had reduced tumor growth rate and improved survival rate, coupled with increased frequencies of IFNγ-producing CD8+ effector T cells in the tumor and draining lymph node." (PMID 30022064, 2018). "Three weeks after HSC transfer, tumors and draining cervical lymph nodes were excised and analyzed for YFP+ expression by CD3+ cells as an indication of activation and IFNγ secretion of T cells in the tumor microenvironment and tumor draining lymph nodes." (PMID 30333482, 2018). "Contact-dependent mechanisms including perforin/granzyme and Fas-FasL, and contact-independent mechanisms such as production of TNFα or IFNγ – are utilized by CD8 T cells in tumor environments with varying degrees of preference." (PMID 29464051, 2018). "As expected, the addition of autologous Tregs suppressed the activation of tumor antigen-reactive T cells (CD3+/CFSElow/IFNγ+) in anti-CD3/anti-CD28-activated aMILs stimulated with tumor antigen-pulsed autologous BM." (PMID 29467463, 2018). "This kind of activation results in the production of cytokines such as interferon gamma (IFN-γ) and tumor necrosis factors, leading to the upregulation of MHC class I expression and tumor suppression." (PMID 30518139, 2018).